SRF (serum response factor)
Diseases named in the same sentence as SRF in open-access papers (continued):
Sharing a sentence is not in itself a finding about the gene and the disease.
ischemia (2 papers, 2014 to 2018). A hypoperfusion of the BLOOD through an organ or tissue caused by a PATHOLOGIC CONSTRICTION or obstruction of its BLOOD VESSELS, or an absence of BLOOD CIRCULATION. "It is therefore expected that t-AUCB can restore the impaired SRF protein after ischemia by suppressing miR-133 levels." (PMID 29843720, 2018).
metabolic syndrome (2 papers, 2021 to 2025). A cluster of metabolic risk factors for CARDIOVASCULAR DISEASES and TYPE 2 DIABETES MELLITUS. "Of note, in a murine model of combined metabolic syndrome (MetS) and atherosclerosis (KKAy+/−ApoE−/−), we recently reported that upregulated TSP1 expression directly associates with increased atherosclerotic lesion burden, accompanied by attenuated LMOD1 and SRF expression in the aortic vasculature." (PMID 40940776, 2025).
Myocardial fibrosis (2 papers, 2017 to 2020). "Myocardin-related transcription factor (MRTF)/serum regulatory protein (SRF) is also an important transcription regulator involved in myocardial fibrosis." (PMID 33328989, 2020). "RhoA, a small Rho family GTPase and an activator of serum response factor (SRF) signaling has also been shown to play an essential role in the control of myocardial fibrosis by regulating cofilins." (PMID 28886070, 2017).
myoepithelial tumor (2 papers, 2017 to 2022). A benign or malignant tumor characterized by the presence of cells that show myoepithelial differentiation. "Here, we further investigated the novel SRF::E2F1 fusion in myoepitheliomas, which, together with the mixed tumors/chondroid syringomas, represent a class of myoepithelial tumors of soft tissue with benign behavior." (PMID 36421692, 2022). "To confirm that this gene expression signature was present and relevant also in SRF fusion-positive tumors, we analyzed the gene expression profile of two myoepitheliomas carrying SRF::E2F1 chimeric fusion with respect to two EWSR1-rearranged MN." (PMID 36421692, 2022). "In this paper, we analyze the specific gene expression profile induced by SRF gene fusion, focusing on the SRF::E2F1 chimeric transcript that we previously identified in two cases of myoepithelial neoplasms of the soft tissues." (PMID 36421692, 2022). "In both L107 and L108, corresponding to one spindle cell and one mixed type myoepithelioma respectively, the rearrangement of SRF gene was observed in about 20% of tumor cells." (PMID 28947952, 2017).
myopericytoma (2 papers, 2017 to 2022). A usually slow growing, subcutaneous nodular neoplasm arising from myopericytes. "SRF fusion events have been observed in myopericytomas, a group of tumors composed of relatively monomorphic, oval-spindle-shaped myoid-like cells, originating from perivascular myoid cells, and showing overlapping morphological features with myofibromas." (PMID 36421692, 2022). "In particular, Antonescu and colleagues detected SRF rearrangements in eight cases of myofibroma/myopericytoma (among which six cases had identical SRF::RELA fusions) displaying a significant downregulation of SRF mRNA." (PMID 36421692, 2022). "Recently, fusion genes involving SRF were detected in some types of mesenchymal tumors, including SRF-NCOA2 in one case of infantile spindle cell rhabdomyosarcoma and SRF-RELA in 7 cases of myofribroma and myopericytoma." (PMID 28947952, 2017).
osteosarcoma (2 papers, 2020 to 2022). A usually aggressive malignant bone-forming mesenchymal neoplasm, predominantly affecting adolescents and young adults. "In osteosarcoma MG63 cells, MRTF/SRF inhibition also led to decreased FGFR1 expression." (PMID 33067523, 2020). "To test whether the MRTF/SRF pathway is also responsible for FGFR1 regulation in cancer cells, we treated the osteosarcoma cell line MG63 with the MRTF/SRF inhibitor." (PMID 33067523, 2020).
Peritoneal Fibrosis (2 papers, 2014 to 2024). Disorder characterized by a wide range of structural changes in PERITONEUM, resulting from fibrogenic or inflammatory processes. "According to this, SRF translocation may be linked to HPMC EMT during the development of peritoneal fibrosis, suggesting that active SRF is necessary for EMT." (PMID 25303231, 2014). "More interestingly, RPL29P2 is only one of the target lncRNAs that can be directly regulated by the transcription factor SRF, a promoter of peritoneal fibrosis." (PMID 38774747, 2024). "Here, we will firstly demonstrate the role and mechanism of SRF in the EMT-derived peritoneal fibrosis." (PMID 25303231, 2014). "SRF-lncRNA RPL29P2 pathway also could presumably enhance peritoneal fibrosis by sponging downstream miRNAs and their target genes or target proteins." (PMID 38774747, 2024). "Thus, a novel SRF/Snail pathway promotes EMT-mediated peritoneal fibrosis and acts as a critical transcription factor during HPMC EMT." (PMID 25303231, 2014). "Finally, our results showed a complete pathway by which the transcription factor SRF could enhance HG-induced peritoneal fibrosis during PD; one pathway functions through direct upregulation of lncRNA RPL29P2 expression." (PMID 38774747, 2024).
psoriasis (2 papers, 2010 to 2022). An autoimmune condition characterized by red, well-delineated plaques with silvery scales that are usually on the extensor surfaces and scalp. "STAT3 is phosphorylated in psoriasis, as well as in a wound-response type model of psoriasis induced by serum response factor-deficiency." (PMID 20300524, 2010). "NFIC, NFYA, POU2F2, FOXA1 and SRF were discovered to be significant in psoriasis in our study after a gene-transcription factor regulatory network and several relevant transcription factors were evaluated." (PMID 36499614, 2022).
scleroderma (2 papers, 2013 to 2021). Scleroderma is a rare autoimmune connective tissue disorder characterized by abnormal hardening of the skin and, sometimes, other organs. "Corresponding changes in the integrity of actin filaments attached to focal adhesions in hypercontractile scleroderma MFBs could directly amplify SMαA gene transcription by altering nuclear translocation of MRTF/SRF complexes that bind and activate the SMαA promoter." (PMID 24832798, 2013).
silicosis (2 papers, 2012 to 2016). Silicosis is a respiratory disease caused by breathing in (inhaling) silica dust. "Expression of α-SMA and SRF was also observed in silicotic nodules and interstitial fibrotic regions in the silicosis model." (PMID 22802960, 2012). "The results of the present study suggest a novel mechanism of action for Ac-SDKP’s beneficial effect in silicosis, which involves attenuation of TGF-β1 and its receptors, SRF and Ang II type 1 receptor (AT1) expression, collagen deposition and myofibroblast differentiation." (PMID 22802960, 2012). "The current study advances the field by demonstrating that Ac-SDKP has an anti-fibrotic effect on silicosis in vivo and in vitro, an effect that involves inhibition of TGF-β induced myofibroblast differentiation, leading to a decrease in SRF, α-SMA and ECM deposition." (PMID 22802960, 2012). "In conclusion, the results of the present study suggest a novel mechanism of action for Ac-SDKP’s beneficial effect in silicosis, which involves attenuation of TGF-β1 and its receptors, SRF and AT1 expression, collagen deposition, and myofibroblast differentiation." (PMID 22802960, 2012). "Ac-SDKP treatment in vivo strongly attenuated 1) silicosis-induced increased expressions of TGF-β1 and RAS signaling, 2) myofibroblast differentiation as indicated by a robust decrease of SRF and α-SMA-positive myofibroblast localization in siliconic nodules in the lung, 3) collagen deposition." (PMID 22802960, 2012).
skeletal muscle tumor (2 papers, 2022). "Thus, the authors report that histological and genomic analyses suggest that the SRF-fused RMS may be a new specific subtype of skeletal muscle tumor." (PMID 36173721, 2022). "Unsupervised gene expression analysis of these cases of SRF-fused RMSs and a cohort comprising different types of RMS showed that they clustered together and away from other skeletal muscle tumor types." (PMID 36421692, 2022).
spindle cell rhabdomyosarcoma (2 papers, 2017 to 2024). An uncommon variant of rhabdomyosarcoma characterized by the presence of whorls of spindle cells forming a storiform pattern. "Fusions between SRF and NCOA2 were detected in some spindle cell rhabdomyosarcomas, while fusions between SRF and NCOA1 or FOXO1 were recently found in “well differentiated” RMS." (PMID 38611033, 2024).
ulcer (2 papers, 2011 to 2021). "The rates of high SRF expression were significantly higher in ulcer tissues than in non-ulcer tissues, including the superficial epithelium (54.2% vs. 30.3%, p < 0.01), mononuclear cells of the lamina propria (69% vs. 58.5%, p = 0.021), and mucosal smooth muscle cells (80% vs. 68.1%, p = 0.024)." (PMID 21410985, 2011).
viral infection (2 papers, 2016 to 2022). "In conditions where caspases are inhibited, for instance in viral infection or chemical perturbation, both CREB1 and SRF induce expression of genes that are pro-survival." (PMID 27125827, 2016).
actinopathies (1 paper, 2021). "List of MKL/SRF-related actinopathies with corresponding protein function, clinical symptoms, and reported functionally affected hematopoietic cells in these patients." (PMID 33692789, 2021). "Here, we summarize these actinopathies and their effect on immune cell function, in an attempt to dissect which MKL/SRF target genes may be important for leukocyte adhesion and trafficking." (PMID 33692789, 2021).
adenoma (1 paper, 2022). A neoplasm arising from the epithelium. "Remarkably, several SRF, AP1 and NFKB target signatures were strongly associated with the Mir34aΔIEC adenoma signature." (PMID 36147476, 2022). "Indeed, GSEA showed that loss of Mir34a in adenomas, and to a lesser extent in tumoroids, was associated with the induction of STAT3, JUN and SRF expression signatures." (PMID 36147476, 2022).
anaplastic carcinoma (1 paper, 2015). "SRF has been found significantly up-regulated in PTC and anaplastic carcinoma as compared to non-tumor thyroid tissues." (PMID 25753578, 2015).
anemia (1 paper, 2023). A reduction in the number of red blood cells, the amount of hemoglobin, and/or the volume of packed red blood cells. "Dual deficiency of mDia1 and mDia2 in mice leads to compromised serum response factor (SRF) signaling, with declined HSPC, severe anemia, and increased animal mortality." (PMID 38157491, 2023).
aortic aneurysm (1 paper, 2025). A ruptured aneurysm located in the wall of the proximal portion of the descending aorta proceeding from the arch of the aorta. "We also discovered that reduction of SRF in the aorta mimics a molecular signature of Ang II treatment, an intervention that causes aortic aneurysm by itself." (PMID 40081573, 2025). "This shows that a proteomic signature of Ang II treatment, known to elicit aortic aneurysms independently of other risk factors, is mimicked by aortic SRF depletion, and together the effects are not additive." (PMID 40081573, 2025).
astrocytomas (1 paper, 2021). "In fact, significant upregulations of MYD88, SRF, JUN, IL1B, TRIF, RIPK1, NLRP3 were detected in GBM cases compared to lower grade astrocytomas (AGII and AGIII)." (PMID 33446690, 2021). "Our transcriptomic data of U87MG cells 12 h after LPS stimulation and the TCGA RNASeq dataset of astrocytoma showed upregulation of genes related to inflammasome and ripoptosome pathways, namely MYD88, NLRP3, RIPK1 and RIPK3, and also SRF, JUN and IL1B, the downstream regulated genes." (PMID 33446690, 2021).
Atherosclerotic lesion (1 paper, 2023). A lesion associated with atherosclerosis, a multifactorial and multipart progressive disease manifested by the focal development within the arterial wall of lesions, that ranges from the development of a fatty streak, plaque progression, and plaque disruption. "MYOCD and SRF complex increases expression of VSMC differentiation markers by binding the CArG box of target promoters to form a MYOCD-SRF-CArG box complex, overexpression of MYOCD up-regulates the expression of multiple contractile genes and prevents atherosclerotic lesions." (PMID 36604627, 2023).
atrial fibrillation (1 paper, 2017). A disorder characterized by an electrocardiographic finding of a supraventricular arrhythmia characterized by the replacement of consistent P waves by rapid oscillations or fibrillatory waves that vary in size, shape and timing and are accompanied by an irregular ventricular response. "As a whole, our data imply that regulatory polymorphisms which alter expression levels of upstream regulators of this gene network (such as Nkx2-5, Mef2a, SRF, Nostrin, Znf451, and Ttn) might predispose to atrial fibrillation." (PMID 28720711, 2017).
bone metastasis (1 paper, 2017). Transfer of a neoplasm from its primary site to bones. "We found that nuclear tissue expression of SRF is significantly dysregulated in bone metastases of men with mCRPC in the post-docetaxel setting; such that low SRF expression is associated with significantly longer time to bone metastasis." (PMID 28249598, 2017).
Brugada syndrome (1 paper, 2022). A genetically heterogeneous condition characterized by complete or incomplete right bundle branch block accompanied by ST elevation in leads V1-V3. "For example, SRF、MYOCD are related to the development of cardiac vascular smooth muscle and molecular regulation of diseases, Mutations in HEY2 cause Brugada syndrome, a rare heart disease." (PMID 36303246, 2022).
cardiac septal defect (1 paper, 2009). "Of these, 3 genes (SRF, EP300, and CREBBP) have been associated with cardiac septal defect." (PMID 19245720, 2009).
cerebral small vessel disease (1 paper, 2019). Cerebral small vessel disease is the term currently used to pathological processes that affect the brain parenchymal circulation (arterioles, capillaries, and veins). "In a recent genetic model of intracerebral hemorrhagic stroke and vascular dementia, cerebral small vessel disease symptoms were elicited by inducible knockdown of the transcription factor, serum response factor (SRF) or its cofactors Myocardin Related Transcription Factor (MRTF-A/-B)." (PMID 31684130, 2019).
chronic renal failure (1 paper, 2021). "SRF is crucial to the maintenance of renal TEC morphology by regulating actin cytoskeleton; moreover, SRF knockout in mouse podocytes led to foot process disappearance and chronic renal failure, suggesting that SRF is critical for kidney function and is likely to play a role in AKI." (PMID 33406503, 2021).
co-infection (1 paper, 2014). "Notably, the salvage of neurons by the co-infection was comparable with that of AdSRF infection alone, indicating that SRF functions downstream of IRF4." (PMID 24510125, 2014).
cutaneous melanoma (1 paper, 2022). A primary melanoma arising from atypical melanocytes in the skin. "SRF/MRTF induces a mesenchymal phenotypic switch in human cutaneous melanoma, and this signaling pathway axis may be a therapeutic target for malignant tumors." (PMID 35075114, 2022).
depression (1 paper, 2021). "The common DEGs of depression and NASH have four TFs, i.e., ATF, SRF, SREBF1, SCRT2." (PMID 34833079, 2021).
diabetic cardiomyopathy (1 paper, 2015). Diabetic cardiomyopathy is a disorder of the heart muscle in people with diabetes. "Recent studies have implicated the activation of SRF in regulating growth during diabetic cardiomyopathy." (PMID 26215257, 2015).
Down syndrome (1 paper, 2015). "Extending our data on DYRK1A, actin and MAL/SRF, publicly available array data of human Down syndrome patient brain tissue demonstrate a reduced expression of numerous MKL1/SRF target genes." (PMID 26310823, 2015).
endometriosis (1 paper, 2025). The growth of functional endometrial tissue in anatomic sites outside the uterine body. "Furthermore, the identification of upregulated genes, such as SIRT1, SBDS, SRF, SPN, P2RX1, TEAD3, and SLITRK3, alongside downregulated genes, including KIF22, KIF25, GAS2L2, and HINT3, highlights a broad transcriptional reprogramming within endometriosis-affected tissues." (PMID 41516028, 2025).
esophageal squamous cell carcinoma (1 paper, 2013). Esophageal squamous cell carcinoma (ESCC) is a type of esophageal carcinoma (EC) that can affect any part of the esophagus, but is usually located in the upper or middle third. "However, the expression and roles of SRF in esophageal squamous cell carcinoma (ESCC) are unclear." (PMID 23426188, 2013).
Friedreich ataxia (1 paper, 2010). An inherited condition that affects the nervous system and causes movement problems. "As expected, frataxin mRNA levels were reduced in the Friedreich ataxia patient lymphoblasts as compared to the control lymphoblasts, while SRF mRNA expression levels were only moderately different between the two cell lines." (PMID 20808827, 2010). "Finally, a ChIP experiment revealed that SRF occupancy of the FXN promoter was reduced in the Friedreich ataxia patient lymphoblasts as compared to the control lymphoblasts." (PMID 20808827, 2010). "Expression of recombinant transcription factors SRF or TFAP2 in two distinct human cell lines, as well as in Friedreich ataxia patient lymphoblasts, resulted in increased frataxin mRNA levels." (PMID 20808827, 2010). "We also checked the mRNA expression levels of SRF, TFAP2, and EGR3 in lymphoblasts derived from an Friedreich ataxia patient (GM16214) and from a healthy control (GM16215)." (PMID 20808827, 2010). "Finally, over-expression of either SRF or TFAP2 significantly increased frataxin mRNA and protein levels in HEK293 cells, and frataxin mRNA levels were also elevated in SH-SY5Y cells and in Friedreich ataxia patient lymphoblasts transfected with SRF or TFAP2." (PMID 20808827, 2010). "To test this hypothesis we over-expressed SRF or TFAP2 in SH SY5Y cells, HEK293 cells, and in lymphoblasts obtained from an Friedreich ataxia patient or from a healthy control individual, and qRT-PCR was performed to assess changes in cellular frataxin mRNA levels following transfection." (PMID 20808827, 2010).
fungal infection (1 paper, 2014). "Together, I demonstrate that the two SRF cofactor families, TCFs and MKLs, regulate distinct subsets of SRF target gene programs during fungal infection in macrophages." (PMID 24758171, 2014). "In the present study, I explored the functions of SRF and its representative cofactors, megakaryoblastic leukemia 1/2 (MKL1/2) and ETS-domain protein 4 (ELK4), during fungal infection challenge in macrophages." (PMID 24758171, 2014).
glaucoma (1 paper, 2018). Increased pressure in the eyeball due to obstruction of the outflow of aqueous humor. "Our study demonstrates proof-of-concept that a nanocarrier-based formulation efficiently achieves a sustained release of a Myocardin-Related Transcription Factor/Serum Response Factor inhibitor and prevents conjunctival fibrosis in an established rabbit model of glaucoma filtration surgery." (PMID 30482196, 2018).
hearing loss (1 paper, 2023). "We believe that this finding is important, as it will provide the foundation for future research on the role of SRF and its downstream components in the long-term maintenance of the hair bundle, with potential implications for progressive types of hearing loss." (PMID 37982489, 2023).
herpes simplex infection (1 paper, 2019). "For the thymus, the NOD-like receptor signaling pathway (PLCB1/MAPK11), the MAPK signaling pathway (SRF/MAPK11), influenza A (RSAD2/MAPK11), and MAPK11 (salmonella, toll-like, herpes simplex infection) were observed." (PMID 30769908, 2019).
hypertrophic cardiomyopathy (1 paper, 2020). A condition in which the myocardium is hypertrophied without an obvious cause. "In mice, the overexpression of mutant SRF resulted in hypertrophic cardiomyopathy in the postnatal heart and increased the expression of fetal cardiac genes." (PMID 32380971, 2020).